IL22 (interleukin 22)
Diseases named in the same sentence as IL22 in open-access papers (continued):
Sharing a sentence is not in itself a finding about the gene and the disease.
infection (continued). "Intriguingly however, we saw no change in the Ki-67 expression of LTi-like ILC3 at day 6 of C. rodentium infection in the colon, despite exhibiting a robust increase in IL-22 production in response to infection as expected." (PMID 37453568, 2023). "In mice infected with IAV, IL-22 protects the integrity of the epithelial barrier and inhibits secondary infection by inducing antimicrobial peptides and intercellular junction proteins expressed in the respiratory epithelium." (PMID 36839448, 2023). "Mitochondrial potential remained elevated—although unchanged—in colonic LTi-like ILC3 in response to C. rodentium infection, and infection-induced IL-22 increases remained sensitive to oligomycin-mediated ablation." (PMID 37453568, 2023). "Nevertheless, in contrast to the upregulated IL-22 expression in patients with a mild infection, the IL-22 levels were decreased remarkably in patients with severe influenza A." (PMID 36839448, 2023). "Together, these studies show that ILC3s and IL-22 are likely more important during the later stage of infection by preventing translocation of pathobionts whereas ILC1s are more important in the early defense against CDI." (PMID 37483638, 2023). "Contrary to the previous case, secreted IL-22 in West Nile virus infection mediates viral dissemination by recruiting neutrophils in infection sites." (PMID 37403036, 2023). "Infection with C. rodentium triggers host-protective IL-22 production from innate lymphoid cells with the recruitment of monocytes and neutrophils early in the course of infection until adaptive immune responses are generated." (PMID 38109366, 2023). "Since several immune subsets can secrete IL-22, we generated mice harboring IL-22Cre/ROSA-26-tdT to fate map IL-22-lineage immune cells during the repair response to PR8 infection." (PMID 37726288, 2023). "A study showed that some IAV-infected mice can inhibit IL-22 production by producing type I interferons (I-IFN), and they were at a higher risk of secondary infection with S. aureus." (PMID 36839448, 2023). "AUD cells also secreted three anti-inflammatory cytokines in response to infection: IL-1RA, IL-10, and IL-22." (PMID 37786945, 2023). "Previous studies have shown that ILC3 can induce the expression of the antimicrobial proteins RegIIIβ and RegIIIγ proteins through the secretion of IL-22 to prevent the infection of S. typhimurium." (PMID 37122757, 2023). "To this end, we explored how loss of Il-22, Il-18, or epithelial Stat3 in mice affects stem cells at the steady state or during AIEC infection." (PMID 35169117, 2022). "As noted, IL-18 expression in Il-22−/− ileum crypts was reduced at the steady state or during AIEC infection." (PMID 35169117, 2022). "At the early stage of infection, IL-22 was rapidly induced in the ileum LP, indicating that IL-22 initiates an innate response to AIEC which is known to target the ileum." (PMID 35169117, 2022). "We previously investigated the role of IL22 signaling in response to infection, and found that IL22 can be upregulated by probiotics and provide a protective effect against pathogens at barrier surfaces." (PMID 35874683, 2022). "For example, in bacteria-induced lung infections, IL-22 acts on the liver to induce the expression of C3 and, thereby, modulates immune responses to control the infection." (PMID 36123595, 2022). "During infection with M. tuberculosis, IL-22 was initially reported to be dispensable for M. tuberculosis control in mouse models." (PMID 35777848, 2022). "We injected CA mycelium suspension and SWFI into the skin of mice and found that serum IL-17, IL-22, and IL-23 in serum were significantly increased on day 1 after CA infection." (PMID 35783379, 2022). "We identified Th17 cells as the major source of IL22 in the bladder, even in the acute phase of infection 24–48 h after UPEC challenge." (PMID 35845169, 2022).
infection (continued). "We furthermore show that IRF-1 is required in order for intestinal ILC3s to produce large amounts of the protective effector cytokine IL-22 early in the course of infection." (PMID 36175404, 2022). "In the acute phase, IL22 is known to recruit neutrophils toward the site of infection as an inflammatory response." (PMID 36078075, 2022). "In the context of infection, IL-22 has been found to increase colonization resistance to the pathobiont vancomycin-resistant enterococci." (PMID 36248804, 2022). "To provide in vivo evidence that IL-22 links IL-18 to upregulate T-cell production of IFNγ in response to AIEC infection, we first investigated how the injection of recombinant IL-18 into Il-22−/− mice contributes to host defence." (PMID 35169117, 2022). "We conclude that mucosal AIEC infection triggers an early IL-22 response cascade which subsequently initiates an IL-18 response circuit." (PMID 35169117, 2022). "By contrast, the Th17-, Th17/IL-22- as well as the Tr1-cluster were more strongly represented in day 8 samples, corresponding to the recovery phase of infection with more need for anti-inflammation and tissue repair." (PMID 35260804, 2022). "Th1/17 cells produce IFN-γ, IL-21, IL-22, and IL-17 during the later stages of infection, with IFN-γ knockout (KO) mice presenting impaired clearance and increased colonic pathology compared to wild-type (WT) mice (25, –, 27)." (PMID 35100877, 2022). "Il17 and Il22 transcripts were reduced in Rorc−/− bladders following infection compared with controls, with similar levels of Csf2." (PMID 35845169, 2022). "Following infection, Th17 cells showed the greatest expression of Il22 transcripts, with some contribution from ILC3s but little detectable Il22 in γδT cells." (PMID 35845169, 2022). "This suggested an important post-transcriptional regulation of IL-23 and IL-22 following PAO1 infection." (PMID 35955566, 2022). "The differences in the time post-infection at which this IL22 was evaluated in these different studies are one of the main causes of this different result during PEDV infection." (PMID 36376395, 2022). "At an early stage of infection, IL-17A and IL-22 from group 3 innate lymphoid cells are required for limiting C. rodentium infection and enhancing host resistance." (PMID 35844574, 2022). "Upon rechallenge, these so-called “trained ILC3s” propagate and exhibit improved IL-22 responses and are able to better control the infection than naïve ILC3s, thus, contributing to long-term mucosal defense." (PMID 36430676, 2022). "Interleukins IL-17 and IL-22 produced by intraepithelial innate lymphoid cells 3 (ILC3) are essential factors to protect the gut against the infection at early stages, whereas a robust Th17 response is required at the later stages to clear the infection." (PMID 35458125, 2022). "ILC3s, which are mainly free from pattern recognition receptors, are activated after infection by cytokines, such as IL-1β and IL-23, secreted from epithelial and in particular myeloid cells and, subsequently, release IL-17 and IL-22 to protect the host." (PMID 36430676, 2022). "One important discovery with respect of delineating mucosal defense mechanisms in response to CR infection is that IL-22 plays an essential role in maintaining gut epithelial barriers." (PMID 36430676, 2022). "By contrast, infection of the lesion with S. aureus and P. aeruginosa led to T cell recruitment/activation, mainly TCRγδ, and IL-17 and IL-22 production, evidencing the involvement of an additional adaptive immune response." (PMID 36275755, 2022). "These cells also generated more IL-22 than naive ILC3s after infection and controlled the infection better." (PMID 36466877, 2022). "Upon infection, pro-inflammatory factors such as IL-1β and IL-23, trigger ILC3s to secrete IL-17 and IL-22, which subsequently enhance airway epithelial barrier function and promote immune responses against S. pneumoniae." (PMID 36305904, 2022).
infection (continued). "The role of IL-22 during rickettsial infections is not yet entirely clear and needs to be further investigated, e.g., what effect IL-22 has on responsive cells during infection." (PMID 35543881, 2022). "Still, a reduction in Th22 cells observed at the second week post-infection, and this finding was accompanied by a reduction in IL-22 in the lung supernatants and in mRNA for IL-22 of L-Kyn treated mice at the two periods of disease assayed." (PMID 33936043, 2021). "CH223191, on the other hand, increased the synthesis of il-6 but reduced il-17 and il-22 mRNA at both post-infection periods, but tgf-β only at 96 hours after infection." (PMID 33936043, 2021). "Endogenous IL-22 plays a role in the intrinsic repair of the injured lung and in clearance of infection." (PMID 34597299, 2021). "Many are triggered in response to SARS-CoV-2 infection, even at later time points distant from the time of infection (e.g., anti-IL-22, subject UMR10, day 29)." (PMID 34521836, 2021). "Day 3 after infection the Il22−/− mice have increased proportions of IFNγ+ cells in the spleen, evident in both CD4 and CD8 T cells as well as γδ T cells." (PMID 33692792, 2021). "Following infection, pro-inflammatory cytokines IL-6, interleukin-22 (IL-22) and interleukin-1 (IL-1) produced by cells of the innate immune system, such as natural killer (NK) cells and macrophages, initiate acute phase response in the liver." (PMID 34571900, 2021). "All saline-treated control mice acutely shed high amounts of viral antigen, whereas all IL-22-treated animals exhibited low levels of fecal viral antigen during the first 5 days post-infection." (PMID 34383769, 2021). "Accordingly, mice lacking CD93, GPR34, or Ffar2 expression on ILC3s showed reduced IL-22 levels in the colon and increased bacterial burden following C. rodentium infection, although mice were able to survive the infection." (PMID 34938670, 2021). "For instance, Type 3 Innate Lymphoid Cells (ILC3s) located in the intestinal lamina propria protect against infection by responding to microbial signals and releasing the cytokine interleukin-22 (IL22), which promotes production of antimicrobial peptides." (PMID 33777849, 2021). "In summary, IL-22 has been shown to reduce lung damage following an infection by influenza A infection and to protect against secondary bacterial infections." (PMID 34659248, 2021). "After infection with A. fumigatus, the amount of IL-17 in Il22−/− lung tissue appeared to be increased (p = 0.06), an effect that was obliterated by pre-treatment with vancomycin." (PMID 33692792, 2021). "To better understand the role of commensal bacteria in host defense against rotavirus, we performed infections of microbiota-depleted mice and we evaluated the antiviral activity of IL-22 under gnotobiotic conditions." (PMID 34383769, 2021). "The infection altered the trafficking and chemokine receptors in ILC3s, reducing the expression of α4β7 integrin in colonic ILC3s and consequently minimizing IL-22 secretion in colon and oral mucosa." (PMID 34659248, 2021). "FICZ enhanced the expression of il-17, il-22, il-10, and tgf-b mRNAs at both periods but reduced il-6 levels at 96 hours of infection." (PMID 33936043, 2021). "In the serum, only IL-10 and IL-13 were significantly increased, while in urine IFN-γ, TNF-α, IL-13, IL-1β, IL-22, and IL-10 were significantly increased in by infection." (PMID 34662329, 2021). "In this case, IL-22 can significantly reduce infection by this pathogen via induction of other antimicrobial peptides such as lipocalin 2 (LCN2) and serum amyloid A1 and A2 (SAA1/2)." (PMID 33851257, 2021). "In recent years, group 3 innate lymphoid cells (ILC3s) have emerged as key mediators of mucosal protection and repair during infection, mainly through IL-17 and IL-22 production." (PMID 33718260, 2021).
infection (continued). "Earlier reported effects of Luteolin on NK cell function were confirmed here in a primary infection model of TB, indicating that Luteolin-induced NK cells further enhance vaccine-induced protection against M. tb, likely in an IL-22-dependent manner." (PMID 34415976, 2021). "As the innate counterparts of T helper 17 (Th17), ILC3s are the early source of interleukin 17 (IL-17) and IL-22 during infections." (PMID 34659248, 2021). "Here, it was shown that infection with Dengue virus 2 (DENV2) in mice resulted in an upregulated expression of IL-22 and IL-17A." (PMID 33851257, 2021). "During infection with S. tm., in line with the observations from the eSPF mice, we detected increased frequencies and absolute numbers of IL-17A-IL-22+ and IL-17A+IL-22+ CD4+ T cells in cecal LPLs from S. tm. infected SFB colonized GF mice." (PMID 34566952, 2021). "IL-22BP has an important role in controlling the biological activity of IL-22 in healthy individuals and during infection or chronic inflammatory diseases." (PMID 34868019, 2021). "On the other hand, S100B inhibition increased the colonic levels of IL-22 during infection (p = 0.008)." (PMID 34568098, 2021). "In tissues treated prior to infection, baseline production of IL-1β, IL-22, CCL3, CCL4 and CCL5 varied between BaL- and LAI-infected explants, possibly reflecting virus difference in cell tropism and subsequent CD4 T cell depletion." (PMID 34835109, 2021). "Further treatment with TLR5 agonist flagellin exacerbated ILC3-mediated IL-22 production, that helped provide defense against lethal infection." (PMID 34804991, 2021). "On day 8 post infection, we observed a prominent population of IL-22-producing T cells, a fraction of which co-produced IL-22 and IL-17, although IL-22 production was transient and low at later time points." (PMID 32719409, 2021). "One study using a murine model of IAV infection followed by S. aureus challenge found that overexpression of IL-23 during infection resulted in enhanced production of IL-17 and IL-22 and promoted bacterial clearance." (PMID 33968082, 2021). "IL-22 can act synergistically with TNFα in response to infection-promoting chemokine expression (including CXCL9, CXCL10 and CCL5) by human keratinocytes." (PMID 34207946, 2021). "Sequential gene deletions showed that EspF and Map effectors are essential for infection by maintaining pathogenicity and inducing IL22 secretion and protective immunity to prevent secondary infection." (PMID 34575120, 2021). "During the immune response to infection, IL-22 and IL-17A are often produced concurrently and at high levels in inflamed tissues." (PMID 34805416, 2021). "We observed a reduced number of MHV-positive cells 2 days of post MHV-GFP infection when organoids were exposed to IL22, indicating that IL22 can indeed reduce viral replication." (PMID 34045640, 2021). "Depletion of CD4+ LTi cells led to a decline in the expression of infection-induced IL-22 and anti-microbial peptides that impaired innate immunity in the intestine." (PMID 34804991, 2021). "Another study describing infections with a different Plasmodium strain, namely, Plasmodium berghei ANKA, demonstrated a critical role of IL-22 in this infectious setting, as IL-22-deficient mice had a more severe disease outcome." (PMID 33851257, 2021). "There was also a significant association of infection with the presence of TNF-α, INF-γ, and IL-22 in the urine." (PMID 34662329, 2021). "24h after infection, anti-IL-22 completely abrogated the effect of FliC on the bacterial load reduction." (PMID 33784296, 2021). "This gap in our knowledge presents us with a growing challenge of understanding how IL-22 signaling can be targeted to combat these infections." (PMID 33851257, 2021). "In order to confirm the implication of IL-22 in the effect of flagellin, we first treated Il22-/- mice with this TLR5 ligand before infection by NTHi." (PMID 33784296, 2021).
infection (continued). "IL-22 mRNA was gradually upregulated during the infection on days 2 and 5 PI and significantly upregulated on day 5 PI (p < 0.001)." (PMID 33441700, 2021). "Using the Pseudomonas aeruginosa model of lung infection, antibody blockade of IL-22 was shown to increase infection, lung damage, and neutrophil accumulation." (PMID 32582219, 2020). "IL-22 up-regulation is reported multiple times in liver patients with chronic Hepatitis B Virus (HBV) or Hepatitis C Virus (HCV) infection." (PMID 33042126, 2020). "In murine model, this amassing of ILC3 is followed by production of IL-22 that defends against lethal infection." (PMID 33042126, 2020). "We found the protective effects of dietary I3C against Cr infection occur by down regulating the proinflammatory response while maintaining IL-22 production." (PMID 33076301, 2020). "When considering the impact of IL-22 within the skin microbiota, the most studied infections are Staphylococcus and Streptococcus-related infections." (PMID 33003458, 2020). "We demonstrated that H. capsulatum infection induces the production of IL-22 in the lungs, which was increased 7 days after infection and corroborates previous studies using conidia or/and yeast forms." (PMID 32517114, 2020). "Cathelicidin antimicrobial peptide (Camp), on the other hand, was upregulated on the 14th day post-infection, possibley due to the increased fungal burden observed at this time-point in Il22−/− mice." (PMID 32517114, 2020). "They showed that conventional DC-derived IL-1β preserves and expands IL-1R1hi IL-22+AhR+ immature NK cells, potentially influencing mucosal innate immunity during infection." (PMID 32647342, 2020). "Predominant cellular sources of IL-22 in response to infection in the lung include Th17 helper cells, γδ T cells, NK cells, and ILCs." (PMID 33003458, 2020). "We confirmed that IL-22 is produced and augmented at the 7th day of infection in the lungs of C57Bl/6 mice, which were infected with 1 × 106 yeasts of a different H. capsulatum strain." (PMID 32517114, 2020). "This rapid production of IL-22, in murine model is implied to retain beneficial role in preserving bronchoalveolar, tracheal, and lung epithelial integrity, and post-infection tissue restoration." (PMID 33042126, 2020). "TLR9 and FoxP3 were up-regulated in dog skin at the early stages of infection and in lymph nodes and significant downregulation of TLR3, TLR4, TLR9, IL-17, IL-22, and FoxP3 transcription was found associated with disease progression." (PMID 33352885, 2020). "IL-22 is produced at the early stage of infection and is essential for the host defense against C. rodentium infection." (PMID 33377111, 2020). "IL-22 provides a link between infection, B-cell recruitment, and humoral autoimmunity, partly mediated by Th17 cells." (PMID 32265904, 2020). "In response to any tissue damage or invasion, IL-22 is known to recruit neutrophils toward the site of infection as an inflammatory response." (PMID 33042126, 2020). "IL-22 has been demonstrated to play a role in infection and immune-mediated diseases related to the skin." (PMID 33003458, 2020). "To define the source of IL-22 following infection, we isolated lymphocytes from the brain and spleen and analyzed the IL-22-expressing subpopulations." (PMID 32843067, 2020). "IL-22 is a member of the IL-10 cytokine family and is produced mainly by innate and adaptive T cells in response to lung injury during infection, allergy, and fibrosis." (PMID 32582219, 2020). "IL-22 was also shown to mediate protection against Mtb during the chronic stages of experimental infection of mice with the W-Beijing strain of Mtb, HN87859." (PMID 33037320, 2020). "Compared to WT animals, both TNF-α and IL-1β increased in the lungs of Il22−/− mice at the 7th day of infection, correlating with increased lung inflammation at the same time point." (PMID 32517114, 2020).